HAS2 (hyaluronan synthase 2)
Diseases named in the same sentence as HAS2 in open-access papers (continued):
Sharing a sentence is not in itself a finding about the gene and the disease.
cancer (80 papers, 2009 to 2025). A tumor composed of atypical neoplastic, often pleomorphic cells that invade other tissues. "We found that low–molecular weight HA activates Yes-associated protein (YAP) in cancer cells, which then releases connective tissue growth factor to further activate CAFs for HAS2 expression." (PMID 39946200, 2025). "HAS2 is particularly significant in developmental processes and is often associated with elevated HA levels in pathological conditions, including cancer." (PMID 41465475, 2025). "Most importantly, mountains of evidence have demonstrated that HAS2 is closely associated with various types of cancer progression." (PMID 36386154, 2022). "Intriguingly, naked mole rats possessing intrinsically decreased hyaluronidase activity and a unique variant of Has2 that synthesizes extremely large HA (>6000 kDa) are benefited with an unusual resistance to cancer and a lifespan of at least 30 years." (PMID 33020183, 2020). "The Has2-deficient Has2Δ/Δ cancer cells displayed greatly reduced Akt phosphorylation at both Ser473 and Thr308 as well as GSK3β phosphorylation at Ser9 as compared with control Has2flox/flox cells." (PMID 31645543, 2019). "Has2-deficient Has2Δ/Δ and control Has2flox/flox cancer cells were treated with cisplatin and the percentage of early and late apoptotic cells was determined by dual staining with fluorescent Annexin V and propidium iodide (PI)." (PMID 31645543, 2019). "In accordance with the reduced phosphorylation of GSK3β, the expression of β-catenin was decreased in Has2-deficient Has2Δ/Δ cancer cells." (PMID 31645543, 2019). "Control Has2flox/flox cancer cells were capable of forming large mammospheres with high efficiency, whereas Has2-deficient Has2Δ/Δ cancer cells mainly formed small mammospheres of 75–150 μm in diameter." (PMID 31645543, 2019). "Has2-deficient Has2Δ/Δ cancer cells exhibited a markedly reduced CD44high/CD24low CSC-like subpopulation as compared with control Has2flox/flox cancer cells." (PMID 31645543, 2019). "ZEB1 and HAS2 expression strongly correlates in various cancer entities and high HAS2 levels associate with an early relapse." (PMID 28086235, 2017). "HAS2 is one of the key enzymes activated by cancer-associated fibroblasts; therefore, cancer cells may stimulate stromal cells to generate HA." (PMID 36613567, 2022). "Furthermore, HAS2 was upregulated in high grade compared to low grade carcinomas and tended to be associated with worse overall and disease-specific survival." (PMID 24069434, 2013). "Adding HA to the HAS2 KO cells reduced these expression levels, further indicating that HA may regulate intracellular nucleotide sugars and their associated functions in cancer cells." (PMID 41461315, 2025). "Taken together, these results indicate that YAP signaling in cancer cells, enhanced by steatotic liver through HAS2-mediated HA production, feeds back to promote CAF activation, including HAS2 upregulation, to further increase the fibrotic TME." (PMID 39946200, 2025). "In summary, these findings suggest that cancer-derived YAP activity contributes to the HAS2/HA/CD44 interaction between CAFs and TAMs and the enhanced interaction of PD-L1 and PD-1 between TAMs and T cells." (PMID 39946200, 2025). "In 3D co-culture, CAFs stimulated the proliferation of cancer cells, and this effect was lost upon HAS2 knockdown." (PMID 41227309, 2025). "We observed that CAFs produced increased levels of hyaluronan and stimulated the proliferation of nearby epithelial TNBC cancer cells, enhanced by the main hyaluronan synthase, HAS2." (PMID 41227309, 2025). "The reduced migratory ability of HAS2 KO cells is a key factor in cancer aggressiveness, mainly due to changes in cell proliferation and movement." (PMID 41461315, 2025). "In naked mole rat HAS2 produces ultra-high-molecular-weight HA with enhanced cancer resistant properties." (PMID 41373700, 2025).
cancer (continued). "In pathological contexts such as cancer, high HAS2/HA levels create a fibrotic, immunosuppressive microenvironment that supports tumor progression and therapeutic resistance." (PMID 41516037, 2025). "Preconditioning with either low-dose TM or 2-DG significantly alleviated cisplatin-induced apoptosis in HA-low Has2+Neo cancer cells." (PMID 38225221, 2024). "For example, overexpression of the naked mole rat version of hyaluronan synthase 2 (Has2) promotes increased cancer resistance and longevity in mice." (PMID 39051470, 2024). "HA-high Has2ΔNeo and HA-low Has2+Neo cancer cells were treated with cisplatin, a platinum-based chemotherapeutic drug, and the numbers of early and late apoptotic cells were determined by dual staining with fluorescent Annexin V and propidium iodide (PI)." (PMID 38225221, 2024). "A pan-cancer analysis, including HCCA, revealed that the significant downregulation of HAS2 contributes to cancer progression and metastasis." (PMID 38932267, 2024). "The naked mole rat (NMR) has a thick ECM and a unique mutation in the hyaluronan synthase 2 (HAS2) gene, which has been linked to the high cancer resistance of the species." (PMID 38004669, 2023). "HAS2-OE promoted U138 cells to secrete more HA, and promoted cancer cell proliferation and migration." (PMID 37636435, 2023). "HAS2, on the other hand, had amplification changes in most cancers, with OV having the highest change frequency (>20%)." (PMID 37636435, 2023). "Our results show that an attenuated, replication-competent HSV vector expressing a foreign ECM-modifying transgene, namely HAS2, provides an effective tool to study and combat cancer in humans." (PMID 38004669, 2023). "The beneficial role of 4MU has also been documented in cancer cell lines where it abrogated cancer cell proliferation and migration through inhibition of HAS2." (PMID 35671866, 2022). "Among all HASs, HAS2 is the most important one implied in both physiological and pathological conditions, including cancer." (PMID 35767191, 2022). "During cancer progression, hyaluronan synthase 2 (HAS2) and the cell migration inducing hyaluronidase 2 (CEMIP2, also known as TMEM2), are upregulated, promoting tumorigenesis." (PMID 35954411, 2022). "Hyaluronan synthase 2 (HAS2) is the most critical synthase in producing hyaluronan and is well known for its involvement in cancer growth, metabolism and metastasis." (PMID 36386154, 2022). "Most importantly, accumulating evidence has demonstrated that HAS2 is overexpressed in various cancers and correlates with a poor prognosis of patients." (PMID 36386154, 2022). "Recently, a large numbers of studies have reported the function and significance of HAS2 in cancer development." (PMID 33892667, 2021). "As previous researches indicate, HAS2 related pathway represents promising novel anti-cancer therapy targets 70-73, which is similar to our conclusion." (PMID 34093817, 2021). "Recently, a novel finding links HAS2 overexpression to altered ER signalling in ER positive MCF-7 cancer cell line." (PMID 33807583, 2021). "HAS2 has been reported to be correlated with the cancer grade and survival of breast cancer patients." (PMID 33506044, 2021). "Previous studies have reported that the expression of SPHK1 and HAS2 was elevated in a variety of malignant tumor tissues." (PMID 33506044, 2021). "Such a protein contributes to the crosstalk between cancer and stromal cells, as it induces the secretion of HA by the surrounding fibroblasts through the up regulation of the hyaluronan synthase 2 gene (HAS2)." (PMID 33807583, 2021). "The same effect on HAS2 expression was described in cancer cells in which the level of HAS3 mRNA was also reduced except for 1 cell line with very low HAS3 expression level." (PMID 32084270, 2020). "Hyaluronan synthase 2 (HAS2) can promote malignant biological behaviors of cancer through activating various intracellular signaling pathways." (PMID 32669974, 2020).
cancer (continued). "Previously, it has been shown that highly invasive cancer cell lines like the MDA-MB-231 have a high expression of HAS2 mRNA and also HYAL2, resulting in higher turnover and accumulation of HA with low molecular weight." (PMID 32824576, 2020). "Taken together, these data indicate that PKCζ is important for the activation of NF-κB, which then regulates the expression of HAS2 and facilitates HA production and cancer cell dissemination via lymphatic drainage." (PMID 30705401, 2019). "In agreement with the clinical data, GFAT1 and Has2 co-expression was evident in aggressive MMTV-PyVT cancer cells." (PMID 31645543, 2019). "Has2 gene disruption reduced the in vivo growth of aggressive cancer cells and attenuated pro-tumorigenic Akt/GSK3β/β-catenin signaling and cisplatin resistance." (PMID 31645543, 2019). "The present study indicated that co-expression of HAS2 and GFAT was highly associated with the aggressive cancer subtypes and strongly correlated with a poor prognosis in advanced cancer patients." (PMID 31645543, 2019). "Of these genes, RHOJ and FSTL1 have particularly been characterized more extensively, whereas ETV1 and HAS2 are newly emerging in the cancer literature." (PMID 31109321, 2019). "We further show that HAS2 driven HA synthesis and signaling via RHAMM is critical in regulating growth of these cancer cells with AGL loss." (PMID 29682180, 2018). "HAS1 mRNA were overexpressed in effusions, in contrast to primary carcinomas and solid metastases, whilst HAS2 mRNA was overexpressed in solid metastases and primary carcinomas compared to effusions and HAS3 mRNA was overexpressed in all subtypes." (PMID 29510526, 2018). "This method has shown confirmation of the HAS2/Irinotecan link in survival which has been shown previously in the literature in different cancers." (PMID 27716027, 2016). "HAS2 mRNA was overexpressed in solid metastases and primary carcinomas compared to effusions (p = 0.043), and HAS3 mRNA was overexpressed in primary carcinomas and effusions compared to solid metastases (p = 0.008)." (PMID 23202930, 2012). "The median of HAS2 mRNA was 51–61% higher in the malignant tumors, compared with normal ovaries, but the variance between individual tumors was extensive." (PMID 19435493, 2009). "The highest HAS2 staining intensities were detected in benign tumors and in grade 1 carcinomas and the intensities (graded into three categories) was significantly different in the histological subgroups (Chi-square P = 0.003)." (PMID 19435493, 2009). "HAS2 controls HA synthesis in HSCs, and HAS2-derived HA promotes fibrosis progression and cancer aggressiveness in breast, esophageal, bile duct, pancreatic, and other cancers." (PMID 39946200, 2025). "Increased HAS2 expression or activity leads to elevated HA synthesis and extrusion, which can promote pathological remodeling processes, such as in pulmonary hypertension and cancer." (PMID 41516037, 2025). "Furthermore, as is corroborated by the in vitro study showing that cancer-derived YAP regulates HAS2 in HSCs, silencing Yap1 in cancer cells reduced Has2 expression in the CAF2 cluster." (PMID 39946200, 2025). "Cancer YAP signaling mediates HAS2 expression and myofibroblastic CAF development." (PMID 39946200, 2025). "Furthermore, a significant association between high CD44, HAS2 and HAS3 mRNA levels and a cancer-cell pericellular HA-deposition pattern was noted." (PMID 36428513, 2022). "Silencing of HAS2 promotes the radiosensitivity of cancer cells." (PMID 33892667, 2021). "Indeed, we found that cancer cell line CM is a source of an uncharacterized protein that can influence HAS2 expression." (PMID 33807583, 2021). "Interestingly, HAS2 knockdown within cancer stem-like (CD44+/CD24−) MDA-MB-231 BoM cells has been shown to reduce both the number and growth of metastatic lesions in vivo." (PMID 32455980, 2020).
cancer (continued). "The introduction of HAS2 catalysis via autophagy as a means of regulating extracellular HA brings forth a greater understanding of the implications of autophagic induction, particularly within the realm of cancer treatment." (PMID 33020183, 2020). "Thus, what are the therapeutic implications of HAS2 catabolism and their ensuing effects on dysregulated angiogenesis in diseases exacerbated by HA accumulation, such as cancer?" (PMID 33020183, 2020). "As elevated levels of stromal HA transduce pro-angiogenic and tumorigenic signals in a multitude of other cancer types, including breast, prostate, ovarian, and lung, the therapeutic benefits of targeting HAS2 via autophagic degradation in these cancer types should be explored." (PMID 33020183, 2020). "4-MU also decreases HAS2/3 expression (60–80% in cancer cell lines)." (PMID 31134064, 2019). "Most of the studies that correlate overexpressed HA in cancer have been focused on HAS2 and HAS3." (PMID 29137675, 2017). "As HAS2 expression and HAS2-generated HA have been shown to promote tumorigenesis, we asked whether HAS2 activity induces ZEB1 expression in cancer cells." (PMID 28086235, 2017). "We have further identified that loss of AGL promotes rapid cancer cell proliferation dependent on extracellular glucose, Serine Hydroxymethyltransferase 2 (SHMT2) driven glycine synthesis and Hyaluronic Acid (HA) Synthase 2 (HAS2) mediated HA synthesis." (PMID 27595989, 2016). "Research from the University of Rochester demonstrated that introducing the naked mole rat’s Has2 gene into regular mice significantly extended their lifespan and enhanced their resistance to cancer and inflammatory diseases, suggesting that Has2 may function as a longevity gene." (PMID 40236823, 2025). "To determine whether partial inhibition of LLO assembly by long-term preconditioning with low-dose TM affects CSC conversion, we pretreated HA-low Has2+Neo cancer cells for 8 days with TM at varying concentrations and evaluated their effects on CSC-like properties." (PMID 38225221, 2024). "In addition, compared with the low-risk group, focal amplification peaks were observed for well-characterized cancer-related genes HAS2 (8q24.13) and PDGFRA (4q12), which might be the reason for the poor outcomes in the high-risk group." (PMID 37663248, 2023). "These ECM molecules have a critical role in tumorigenesis and angiogenesis via HAS2 turnover, and they are currently under investigation for stopping neoangiogenesis; this finding can be a promising target for controlling the HA-derived vessel sprouting within the cancer stroma." (PMID 36765756, 2023). "Thus HAS2 might utilize some hyaluronan-independent mechanisms that increase cancer cells tumorigenesis." (PMID 29914429, 2018). "Decreased hyaluronan synthesis due to knockdown of HAS2 probably explains some of the anti-tumorigenic effects, but HAS2 might harbor some other mechanisms too such as regulating TGFβ-induced epithelial-mesenchymal transition or increasing cancer cell invasion by downregulation of TIMP-1." (PMID 29914429, 2018). "To understand the functional role of hyaluronan in TNBC, we therefore knocked down HAS2 and analysed the effect on the CAFs and the TNBC cancer cells." (PMID 41227309, 2025). "The study comprehensively describes the characteristics of HAS1, HAS2, and HAS3 in cancers using public databases and tools, to identify the potential biological pathways involved at the molecular, protein, cellular, and clinical sample levels." (PMID 37636435, 2023). "In this study, a pan-cancer analysis of the three enzymes called hyaluronan synthases (HAS1, HAS2, and HAS3) that produce HA was performed." (PMID 37636435, 2023). "Some types of cancer cells express hyaluronan synthases (HAS1, HAS2, and HAS3), as well as embryonic cells, and HAS2-CD44 signaling is considered to play a vital role in malignant progression." (PMID 37064130, 2023).
cancer (continued). "HAS1 and HAS2, as key enzymes in HA synthesis, are significantly positively correlated with the degree of CAF infiltration in most cancers, but HAS1 is significantly negatively correlated with the degree of CAF infiltration in LGG." (PMID 37636435, 2023). "In the present study, we propose that Etv1 is a nuclear transcriptional factor suppressed by the TGIF1 repressor, and Etv1 upregulation mediated by TGIF1 ablation confers to increase Has2 activity and activate the HA/CD44 cancer stemness pathway in PDAC." (PMID 31109321, 2019). "Transforming growth factor b (TGFβ) induced HA synthesis via upregulation of hyaluronan synthase 2 (HAS2) potentiates epithelial- mesenchymal transition (EMT) assisting in the migration and metastasis of cancer cells." (PMID 29535843, 2018). "The reduced migration capacity of cancer cells after Apixaban incubation may indicate a reduced malignancy potential in some cancer cell lines, though our results on MMPs and HAS2 do not clarify the mechanisms potentially associated with a reduced invasion capacity." (PMID 29023465, 2017). "HAS2 overexpression was sufficient to induce EMT in normal epithelial cells, and was demonstrated to mediate TGF-β1-induced EMT in several cancers." (PMID 27574697, 2016). "In cancer, ransforming growth factor β (TGF-β)and reticular activating system, (RAS) signaling have been shown to work together to activate “primed” enhancers that drive HAS2 expression, thereby promoting metastasis." (PMID 41373700, 2025). "Studies have shown that CCNA2, HAS2 and TIMP1 can regulate the cell cycle of cancer cells." (PMID 33619234, 2021). "Furthermore, there was an autocrine feedback loops among ESRP1, HAS2, CD44, and ZEB1 in the aberrant activation of EMT, which acted in the dynamics of EMT in cancer metastasis." (PMID 32211324, 2020). "Moreover, the Has2 enzyme is involved in hyaluronan (HA) synthesis and enhances the HA/CD44 cancer stemness pathway." (PMID 31109321, 2019). "The silencing of GFAT reduced CD44high/CD24low cancer stem cell (CSC)-like subpopulations, aldehyde dehydrogenase-positive cell populations, and mammosphere size, which were further diminished by gene targeting of Has2." (PMID 31645543, 2019). "Cancer patients where AGL expression is low and HAS2 or RHAMM is overexpressed might be the best patient cohort who would responds to HA synthesis or signaling inhibitors." (PMID 29682180, 2018). "Among three isoenzymes, HAS2 and HAS3 have been shown to produce extracellular HA, whereas HA synthesized by HAS1 has been identified in both intra- and extracellular compartments of cancer cells." (PMID 29137675, 2017). "4MU, like HAS2, has been shown to reduce CD44 and RHAMM receptor expression in cancer cells." (PMID 27595989, 2016). "Importantly, we clarified the pivotal role of HAS2, which probably led to disruption in the expression of MMP1 and TIMP1 and consequently promoted cancer progression." (PMID 27884164, 2016). "HAS expression patterns may be somewhat cancer specific; for example, metastatic prostate and colon cancer express higher levels of HAS3 than HAS2." (PMID 25852691, 2015). "A dose-dependent reduction in the mRNA levels of HAS2 or HAS3 was observed in all the cancer cell lines examined, which is not consistent with the findings of the current study, in which Has1 and Has3 mRNA levels increased after treatment with MU." (PMID 22045192, 2011). "Expression of HAS2 was not significantly changed in malignant tumors or the postmenopausal or hyperplastic tissues as compared to normal endometrium." (PMID 20875124, 2010). "A few of the samples showed high expression levels of HAS2, but most of the cancers showed no elevation in the expression of any of the HAS genes." (PMID 19435493, 2009). "There was little HAS1 mRNA, no consistent upregulation of HAS2 in the cancers, and the median values of HAS3 mRNA were actually lower in cancers than controls." (PMID 19435493, 2009).